LINC00319 (long independently transcribed non-coding RNA 319)
Synonyms: PRED49; FLJ38036; LOC124900467; C21orf125; NCRNA00319
Gene: Long non-coding RNA gene on chromosome 21 (43,446,565 to 43,453,902, forward strand). Ensembl gene ENSG00000188660.
Diseases named in the same sentence as LINC00319 in open-access papers:
LINC00319 is named in the same sentence as 10 diseases in open-access papers, as found by Europe PMC text mining. Sharing a sentence is not in itself a finding about the gene and the disease. The quoted sentences say what the papers report.
ovarian carcinoma (4 papers, 2020 to 2025). A malignant neoplasm originating from the surface ovarian epithelium. "LncRNA-plasmacytoma variant translocation I (PVT1), metastasis-associated lung adenocarcinoma transcript 1 (MALAT1), and LINC00319 were demonstrated to be involved in ovarian cancer cell proliferation, migration, and invasion by acting as a ceRNA." (PMID 34900667, 2021). "The downregulation of LINC00319 was able to curtail the malignant activity of ovarian cancer cells by repressing the expression of NACC1 through miR-423-5p." (PMID 40999508, 2025). "LINC00319 is located in the intergenic region of chromosome 21 and acts as an oncogene in various tumors including ovarian cancer, cutaneous squamous cell carcinoma, glioma, and lung cancer." (PMID 32948745, 2020). "Similarly, LINC00319 has also been demonstrated to encourage proliferation, migration and invasion of ovarian cancer cells, thus exacerbating the progression and development of ovarian cancer." (PMID 33585183, 2020).
glioma (3 papers, 2020 to 2024). A benign or malignant brain and spinal cord tumor that arises from glial cells (astrocytes, oligodendrocytes, ependymal cells). "For example, linc00319 expresses at a high level in glioma and is significantly associated with poor prognosis of glioma patients, while knockdown of linc00319 impairs cell proliferation, arrests cell cycle and induces cell apoptosis of glioma cells." (PMID 32776110, 2020). "In addition, LINC00319 was also found to accelerate tumor growth and metastasis in glioma and lung cancer." (PMID 32948745, 2020). "Further study has found that LinC00319 can directly bind to TATA box binding protein related factor 1 (TAF1) and further regulate HMGA2 to promote glioma cell proliferation, accelerate cell cycle, and inhibit glioma cell apoptosis, providing new ideas for molecular targeted therapy of glioma." (PMID 38967893, 2024).
bladder cancer (2 papers, 2020 to 2021). "LINC00319 has been reported to participate in the tumorigenesis of nasopharyngeal carcinoma, bladder cancer, and lung cancer through sponging miRNA16–18." (PMID 32948745, 2020).
cutaneous squamous cell carcinoma (2 papers, 2020 to 2021). "Previously, the upregulation of LINC00319 was found to be associated with a poor prognosis of cutaneous squamous cell carcinoma patients." (PMID 32948745, 2020). "LINC00319 expression has been identified to be upregulated in cutaneous squamous cell carcinoma with studies suggesting its relationship with poor prognosis is due to its ability to promote cell proliferation and invasion;8 a similar trend was observed in the data of the current study." (PMID 34408262, 2021).
lung carcinoma (2 papers, 2020 to 2021). "In addition, in the setting of lung cancers, reports have shown that LINC00319 is highly expressed in cell lines and is associated with cellular progression, including cell proliferation and invasion, by reducing the expression of microRNA-3224." (PMID 34408262, 2021).
cervical cancer (1 paper, 2021). A primary or metastatic malignant neoplasm involving the cervix. "Linc00319 silencing has suppressed cell proliferation, invasion, and migration of cervical cancer cells." (PMID 33768092, 2021). "In cervical cancer cells, the expression of linc00319 has been increased." (PMID 33768092, 2021). "Also, IRAIN, Linc00319, and DLEU1 through negatively regulating IGF-1R could cause breast cancer, cervical cancer, and hepatocellular carcinoma." (PMID 33768092, 2021).
tumor (5 papers, 2019 to 2023). "LINC00319 was shown to promote the proliferative, migratory and invasive capabilities of tumor cells by stabilizing SIRT6 or by interacting with miR-1207, miR-450 and miR-32." (PMID 32194636, 2020). "In contrast, LINC00319 is down‐regulated with age and promotes tumor growth via transcriptional silencing." (PMID 31168962, 2019). "Our results indicated that increased LINC00319 expression promoted the proliferation, invasion, and self-renewal abilities of CSCs in LSCC and facilitated tumor growth." (PMID 34408262, 2021).
cancer (2 papers, 2020 to 2021). A tumor composed of atypical neoplastic, often pleomorphic cells that invade other tissues. "Recent data has revealed that dysregulated LINC00319 was implicated in the progression of many cancers by involving a ceRNA network." (PMID 32948745, 2020). "In accordance with the expression pattern of LINC00319 shown in other types of cancers, the present study using qRT-PCR assay showed the increased level of LINC00319 mRNA in OSCC cells." (PMID 32948745, 2020). "HE staining showed that the cancer cells in the LINC00319-silenced group had an irregular shape, small nuclei, and displayed lesser neovasculature." (PMID 32948745, 2020). "Taken together, these data show that downregulating LINC00319 in CD133+CD144+ TU177 cells may serve as a potential anticancer regimen by inhibiting the proliferation and invasion of cancer stem cells in LSCC." (PMID 34408262, 2021).
LINC00319 also shares sentences with these, for which no sentence is quoted: laryngeal squamous cell carcinoma (1 paper); nasopharyngeal carcinoma (1).